AARD (alanine and arginine rich domain containing protein)
Synonyms: C8orf85; LOC441376
Tractability: No criterion of Open Targets' tractability assessment is met for any kind of drug.
Gene: Protein-coding gene on chromosome 8 (116,938,207 to 116,944,487, forward strand). Ensembl gene ENSG00000205002.
Subcellular location (Human Protein Atlas): Lipid droplets
Gene Ontology:
Molecular function: protein binding
Genetic constraint (gnomAD): Loss-of-function variants: 9 observed, 8.74 expected, observed/expected ratio (o/e) 1.03, 90% interval 0.62 to 1.72. That is too few expected variants to judge how well the gene tolerates losing a copy. Missense variants: 236 observed, 202.18 expected, observed/expected ratio (o/e) 1.17, 90% interval 1.05 to 1.3. Synonymous variants: 91 observed, 92.02 expected, observed/expected ratio (o/e) 0.99, 90% interval 0.83 to 1.18.
Homologues: Orthologues: chimpanzee AARD (97% identical), macaque AARD (90% identical), pig AARD (59% identical), rabbit AARD (58% identical), mouse Aard (56% identical), rat Aard (56% identical). Paralogues in human: FAM167A (23% identical), FAM167B (20% identical), C20orf202 (12% identical).